METTL14 (methyltransferase 14, N6-adenosine-methyltransferase non-catalytic subunit)
Diseases named in the same sentence as METTL14 in open-access papers (continued):
Sharing a sentence is not in itself a finding about the gene and the disease.
tumor (continued). "METTL14 expression is upregulated in CC, and knocking down METTL14 significantly inhibited tumor growth and invasion." (PMID 37474926, 2023). "The miR-17-5p group exhibited larger tumors, while METTL14 opposed the enhancing effects on tumor mass and weight under the treatment of 5-FU." (PMID 36810285, 2023). "The anticancer immunological response mediated by delicaflavone was reversed in tumor-bearing mice by overexpression of the N6-methyladenosine (m6A) transferase Mettl3/Mettl14." (PMID 37175435, 2023). "On one hand, inhibition of METTL3 or METTL14 expression can reduce m6A level, enhance GSCs growth and self-renewal in vitro, as well as promote tumor-forming ability of GSCs in vivo." (PMID 36683086, 2023). "Approximately 2 weeks after subcutaneous implantation of these cells into mice, slower tumor growth was observed in the METTL14 OE/miR-17-5p groups than in the NC/miR-17-5p group." (PMID 36810285, 2023). "SIRT6, another protein serving as a tumor suppressor via inhibiting aerobic glycolysis in diethylnitrosamine-induced liver tumorigenesis, is also regulated by the METTL14-m6A-USP48 axis." (PMID 37015927, 2023). "Methyltransferase-like 14 (METTL14) has a dual function as both tumor promoter and inhibitor in cancer pathogenesis." (PMID 37915034, 2023). "Tumor formation in nude mice demonstrated METTL14/PLAGL2/β-catenin axis promoted NSCLC development in vivo." (PMID 36873735, 2023). "As a key component of m6A RNA deposits, METTL14 is identified downregulated in BC and influences tumour aggressiveness." (PMID 37284313, 2023). "For example, METTL3 or METTL14 deficiency in colorectal carcinoma cells increases recruitment of CD8+ T cells and the levels of IFN-γ, CXCL9, and CXCL10 in the tumor microenvironment." (PMID 37485079, 2023). "The expression of circSTX6 was regulated by METTL14‐mediated m6A modification, and circSTX6 was prevalently upregulated in tumour tissues, correlating with adverse outcomes in HCC patients." (PMID 37877357, 2023). "SW480 cells with METTL14 deficiency exhibited marked CRC tumor growth, as shown by the tumor weight and growth curves of these groups compared with those of the control groups." (PMID 36810285, 2023). "In some other independent studies on the same cancer, METTL3 and METTL14 also have an opposite effect on tumor process." (PMID 36970605, 2023). "The role of METTL14 in tumor development is not limited to its effect on mRNA stability; it also affects ncRNAs such as circRNAs." (PMID 37965577, 2023). "Alterations in the expression of m6A writers (i.e. METTL3 and METTL14), erasers (i.e. FTO) or readers (i.e. YTHDC2 and YTHDF1), for example, are associated with tumor-suppressive or tumor-promoting scenarios." (PMID 36866275, 2023). "Unexpectedly, METTL3 and METTL14 showed dissimilar effects on tumor-infiltrating CD8+ T cell in the TME of breast cancer 112,113." (PMID 37928272, 2023). "In another study, the consumption of METTL3 or METTL14 in CT26 tumor mice with anti-PD-1 therapy significantly slowed tumor proliferation and prolonged the survival rate." (PMID 37427112, 2023). "By utilizing single cell sequencing, METTL14 deficiency in a subset of TAMs distiquished by the marker C1q+, impairs the antitumor response by driving CD8+ T cell dysfunction, resulting in CRC tumor growth." (PMID 37015927, 2023). "Investigation on the upstream regulatory mechanisms of METTL14 dysregulation helps us to better comprehend the biological role of METTL14 in cancers and provides possible therapeutic targets for anti-tumor therapy." (PMID 35974338, 2022).
tumor (continued). "METTL14 knockdown disrupted the methyltransferase complex and decreased m6A abundance, impairing tumor aggressiveness." (PMID 35048498, 2022). "In vitro experiments also demonstrated that METTL14 knockdown promotes tumor cell proliferation and invasion by activating PI3K/Akt signaling, which is consistent with our pathway enrichment results." (PMID 35223847, 2022). "On the contrary, overexpression of METTL14 amplified the proliferation and colony numbers of tumor cells." (PMID 35354789, 2022). "In PCa, higher METTL14 expression has been correlated with poor prognosis in PCa patients, with knockdown of METTL14 attenuating tumour proliferation both in vitro and in vivo." (PMID 36733939, 2022). "Based on our work, we further identified THBS1 as the potential target gene of METTL14 and functions as the tumor suppressor in PCa." (PMID 35354789, 2022). "Like METTL3, METTL14 has been shown to act both as a tumour suppressor and an oncogene in regulating the development of a number of different tumour types." (PMID 36733939, 2022). "Recent studies found that METTL14, METTL3, and their target genes, Spred2 and Irakm, in macrophages are associated with tumor progression." (PMID 35296338, 2022). "The mRNA and protein expression of METTL14 were negatively correlated with TROAP in the tumor tissues dissected from the nude mice." (PMID 35251990, 2022). "Collectively, we propose methyltransferase METTL14 as a key component for m6A RNA deposit and that it is closely related to BlCa progression, playing an important role in tumor aggressiveness." (PMID 35048498, 2022). "METTL3 and METTL14 cooperate to promote m6A RNA modification, but they have been reported to demonstrate opposite effects on the occurrence of the same tumor." (PMID 36561529, 2022). "The present work is a review of the role of METTL14 both as a tumor suppressor and a tumor promoter in the oncogenesis and progression of various tumors, as well as the potential molecular mechanisms." (PMID 34904301, 2022). "In most tumors, METTL14 acts as an antioncogene, downregulating the level of m6A in tumor cells by exerting its function as a m6A methyltransferase to suppress the occurrence and progression of tumors." (PMID 35115038, 2022). "We further demonstrated that the cell viability and colony formation capacity of the tumor cells were reduced with METTL14 overexpression." (PMID 35251990, 2022). "Whilst some previous studies have indicated that METTL14 can have a tumour suppressor role in certain cancer contexts and types, the current study identified elevated METTL14 expression in PCa cell lines compared with the non-malignant control." (PMID 36733939, 2022). "Then after 6 weeks, the data showed that the depletion of METTL14 significantly restricted the tumor growth." (PMID 35354789, 2022). "The abnormal expression of METTL14, an m6A modification editor, affects tumor cell proliferation, metastasis, tumor stem cell self‐renewal, and chemotherapy resistance." (PMID 34904301, 2022). "This study focuses on the impact of METTL14 and its related genes on BCa cell biological behaviors and tumor metastasis." (PMID 36288387, 2022). "In metastatic HCC, METTL14 interacts with the microprocessor protein DiGeorge syndrome critical region 8 (DGCR8) to suppress tumor metastasis." (PMID 35974338, 2022). "This study provides evidence that METTL14 is overexpressed in CM tissues, promotes migration and invasion of CM cells in vitro and enhances tumour metastasis in vivo." (PMID 36264762, 2022). "It was demonstrated the number of metastatic tumours in the lungs in the METTL14‐knockdown group showed decreased tendency, suggesting that METTL14 can enhance the metastasis of CM cells both in vitro and in vivo." (PMID 36264762, 2022). "According to previous findings, the m6A writer, METTL14, acts as a tumor-suppressing factor in ccRCC, characterized by inhibiting metastasis of cancer cells by repressing expression of BPTF and P2RX6." (PMID 35305660, 2022).
tumor (continued). "Inhibition of METTL14 not only promoted the proliferation and accumulation of cytotoxic tumor-infiltrating CD8 + T cells, but also induced the secretion of IFN-C, CXCL9, and CXCL10, thus enhanced immunotherapy efficacy and suppressed cancer proliferation." (PMID 35974338, 2022). "Considering that the metastasis ability of tumor cells is also a crucial factor for both tumor progression and patients’ prognosis, further studies will be performed to explore how METTL14 affects the metastasis ability of PCa tumor cells in the future." (PMID 35354789, 2022). "Although METTL14 has a tumor suppressor effect in most cancer types, it has also been found to act as a contributing factor to tumorigenesis and development." (PMID 34904301, 2022). "In recent years, the effects of tumor cells’ METTL14 on the immune cells of the TME have only begun to be revealed." (PMID 35296338, 2022). "It was reported that METTL14 regulates tumor proliferation, metastasis, and self‐renewal, and plays a part in tumorigenesis, tumor progression, and other processes." (PMID 34904301, 2022). "For instance, METTL3 and METTL14, as methylating enzymes, regulate a variety of malignant events, including tumor proliferation, metastasis, stemness maintenance, and chemotherapy resistance." (PMID 36438800, 2022). "HE and IHC staining indicated that the tumor proliferation marker Ki-67 was downregulated in METTl14 transfected group compared with the NC group." (PMID 35164771, 2022). "METTL3 was shown to be much more highly expressed in CRC tumor tissues, while METTL14 was much more expressed in normal CRC tissues." (PMID 36230970, 2022). "Aberrant METTL14 exon 10 exclusion enhances the N6-methyladenosine modification in PDAC cells which promotes tumor metastasis, while aberrant splicing of Cyclin L2 exon 6.3 promotes tumor proliferation." (PMID 36140826, 2022). "Particularly, METTL14 expression was found to be significantly related to overall survival, tumor T stage, relapse rate, and tumor microenvironment of PCa patients, showing that it has important prognostic value." (PMID 35559023, 2022). "We noticed that the cytosolic/nuclear ratio of METTL14 is always consistent with the ratio of METTL3 across tumor cell lines." (PMID 36289222, 2022). "Here, we for the first time illustrate that METTL14 serves as the oncogene in the pathological processes of PCa and accelerates tumor proliferation in PCa." (PMID 35354789, 2022). "Here, the authors find 12 significantly mutated genes and 5 focal CNA regions were found in perihilar cholangiocarcinoma, and identified METTL14 to have a potential tumour suppressive role." (PMID 35650238, 2022). "METTL14 knockdown led to disruption of the remaining methyltransferase complex and a decrease in m6A abundance, as well as overall reduced tumor aggressiveness (decreased cell invasion and migration capacity and increased apoptosis)." (PMID 35048498, 2022). "By interacting with DGCR8, METTL14 positively regulates the expression of pre-miR-126, and miR-126 also reversely inhibits the inhibitory effect of METTL14 on tumor cell metastasis." (PMID 35022030, 2022). "METTL14 overexpression prohibits BCa cell migration, invasion in vitro and tumor metastasis in vivo." (PMID 36288387, 2022). "In this study, we found that METTL14 functions as a tumor suppressor in ccRCC metastasis using patients’ samples from our own cohort and a ccRCC tissue microarray, as well as in vitro and in vivo experiments." (PMID 35036065, 2022). "The growth curve demonstrated that, the tumors in METTl14 transfected group presented a reduction in a time dependent manner, and the tumor volume and weight were alleviated in METTl14 transfected group compared with the NC group." (PMID 35164771, 2022). "ZC3H13 and METTL14 were strongly related to APC (an antagonist of the Wnt signaling pathway), meaning that ZC3H13 and METTL14 are involved in the regulation of invasion, proliferation, and metastasis of tumor cells." (PMID 36261786, 2022).
tumor (continued). "RNA-seq analysis showed that compared to the control group, 204 genes (log2 FC < −0.5) were downregulated, and 172 genes (log2 FC > 0.5) were upregulated when METTL14 was knocked down in tumor cells." (PMID 35354789, 2022). "Beyond inhibiting metastasis, METTL14 serves as a tumor suppressor involved in various biological processes." (PMID 35974338, 2022). "To further verify the diagnostic value of prognosis-related m6A regulators, we investigated the potential correlation between METTL14 expression and the tumor microenvironment." (PMID 35559023, 2022). "METTL14 positively regulates the maturation of the tumor suppressors miR-126, miR-375, and miR-19a, as well as inhibiting invasion and migration in several cancers." (PMID 36561529, 2022). "We found that wide‐type METTL14 overexpression repressed tumorigenesis with prominently lower tumour volumes compared with control group." (PMID 34609072, 2021). "By comparing 50 normal and 374 tumor tissues, METTL14, YTHDC1, ZC3H13, ALKBH5, YTHDF2, and RBM15 had extremely lower expression in tumor tissues (p < 0.001)." (PMID 34277622, 2021). "Inhibiting the expressions of m6A methyltransferase METTL3 or METTL14 can reduce the m6A level and promote the tumor formation ability of GSCs in vivo." (PMID 34281602, 2021). "To identify the function of METTL14 in tumor proliferation, we knocked down METTL14 in PC cell lines (BxPC-3 and SW1990) and HPDE6-C7 cell using shRNAs (shMETTL14-09, shMETTL14-10, and shMETTL14-11)." (PMID 34330301, 2021). "As presented in 72 pairs of ccRCC and matched normal tissues, METTL14 had a low expression in tumor tissues in TCGA dataset (p = 0.004)." (PMID 33430867, 2021). "For instance, the downregulation of METTL14 is closely related to malignant progression and poor recurrence-free survival and overall survival of patients, suggesting the potential role of METTL14 in predicting tumor metastasis and recurrence." (PMID 33456561, 2021). "A STAD liver metastasis orthotopic tumor model for detecting METTL14’s effect was executed on CRC metastasis in vivo." (PMID 34476213, 2021). "For instance, in vitro and in vivo experiments have shown that METTL14 (methyltransferase-like 14) inhibition significantly promoted tumor metastasis by modulating the primary microRNA 126 process in an m6A-dependent manner." (PMID 34660788, 2021). "In this study, the authors showed that METTL14 expression induced an increase in pri-miR-126 expression, suppressing tumour metastases." (PMID 33461542, 2021). "Tumor weights were also significantly lower in gemcitabine treated group as compared to the tumors harvested from control group after METTL14 depletion." (PMID 34458141, 2021). "The current research has further identified METTL14-mediated N6-methyladenosine modification of PTEN mRNA controlling tumor growth and metastasis in STAD, which implied that METTL14 is a potential therapeutic target in STAD." (PMID 34476213, 2021). "METTL14 suppresses the metastatic potential of HCC by modulating m6A-dependent tumor-suppressor primary miRNA processing." (PMID 34277630, 2021). "Through comprehensive bioinformatics analysis, the correlation and potential mechanisms between METTL14 and tumor immune were further clarified." (PMID 34122497, 2021). "Combined with TIICs analysis, we found that the METTL14/CCL5/Tregs axis was a potential tumor immune regulative pathway in ccRCC." (PMID 34122497, 2021). "Although METTL14, another writer protein, was identified mainly as a tumor suppressor in cancers 13, it functions as an oncogene in acute myeloid leukemia 57 and breast cancer." (PMID 34239358, 2021). "Our study uncovered that METTL14 was down-regulated in ccRCC and significantly negatively correlated to tumor stage." (PMID 34122497, 2021). "The m6A regulators cluster with the best prognosis had significantly increased METTL14 and ZC3H13 expression and was characterized by low mutation rate, tumor heterogeneity, and neoantigens." (PMID 34531875, 2021).
tumor (continued). "Lower expression of METTL14 was significantly associated with poorer prognosis in KIRC patients, which showed that METTL14 acts as a tumor suppressor gene in the tumorigenesis of KIRC." (PMID 34150845, 2021). "Methyltransferase-like 14 (METTL14), a notable RNA N6-adenosine methyltransferase (m6A), plays a significant role in the growth of tumor through controlling the RNA working." (PMID 34476213, 2021). "The regulation of METTL14 expression on the metastatic behavior of tumor cells varies in different tumors." (PMID 34011074, 2021). "METTL14, another vital component of the m6A writer complex, has been identified as a tumor suppressor in multiple types of malignancies." (PMID 34239358, 2021). "For instance, METTL14, a component of m6A methyltransferase complex, plays a tumor-suppressor role in HCC, in which METTL14 and m6A levels were decreased in HCC tissues." (PMID 34900723, 2021). "To address if SLC7A11 inhibition can mimic the tumour‐suppressive function of METTL14, we first detected the effect of SLC7A11 knockdown on ferroptosis induction." (PMID 34609072, 2021). "METTL14 knockout promotes the proliferation, self-renewal, metastasis, and initiation of tumour cells, while overexpression plays an adverse role." (PMID 35004679, 2021). "Prognosis of the GC patients was obviously correlated with tumor size (p < 0.001), pT stage (p < 0.001), pN stage (p < 0.001), M stage (p < 0.001), and METTL14 expression level (p < 0.001) in univariate analysis." (PMID 33314339, 2021). "Growing evidence has demonstrated that m6A modification is closely associated with tumorigenesis, tumor differentiation, tumor proliferation, tumor invasion and worse survival in BC patients, including METTL3, METTL14, WTAP, ALKBH5, IGF2BP2, IGF2BP3, and FTO." (PMID 33926554, 2021). "In CRC, Previous studies have indicated that METTL14 suppressed the tumor progression by regulating miR-375, lncRNA XIST and SOX4, respectively." (PMID 34916487, 2021). "METTL14 performed tumor suppressor functions similar to that of METTL3 in the development of GSCs by targeting mRNA levels of ADAM19, EPHA3 and KLF4." (PMID 34521394, 2021). "Three important subunits of the m6A methyltransferase complex, methyltransferase-like 3 (METTL3), METTL14, and WT1 associated protein (WTAP), were found different expression in tumor tissues." (PMID 34178650, 2021). "It has been reported that METTL14 acts as a tumor suppressor for inhibiting tumor metastasis via regulating miRNA in hepatocellular carcinoma." (PMID 34122497, 2021). "Studies further discovered a role of m6A methylases in BC; consistently, they also identified the writers ZC3H13 and METTL14, which functioned as tumor suppressor genes in BC patients using TCGA data." (PMID 34381710, 2021). "Advanced stages of the tumor are negatively correlated to the mRNA levels of Methyltransferase-like 14 (METTL-14), sequestered by circulating RNAs, and resulting in the methylation of PTEN, a frequently mutated gene in ccRCC." (PMID 34440329, 2021). "Herein, we reported that hypoxia induced suppression of METTL14 which played a tumour‐suppressive role in HCC via induction of ferroptosis." (PMID 34609072, 2021). "Tumor volumes were studied for the nude mice that were subcutaneously given METTL14 overexpression HGC-27 cells (METTL14-OE) or control (NC) transfected HGC-27 cells." (PMID 34476213, 2021). "Subcutaneous xeno transplantation model and STAD liver metastasis orthotopic tumor model were used to study METTL14 in STAD in vivo." (PMID 34476213, 2021). "Meanwhile, forced expression of METTL14‐R298P mutant lost the tumour‐repressive role in xenograft mice." (PMID 34609072, 2021). "Nevertheless, the purpose and molecular mechanisms of METTL14 in STAD’s tumor progression is still unclear." (PMID 34476213, 2021). "We observed that METTL14 expression is positively correlated with overall survival (OS) and tumor immune cell infiltration." (PMID 34221955, 2021).